MIR3147 (microRNA 3147)
Synonyms: hsa-mir-3147; mir-3147
Gene: MicroRNA gene on chromosome 7 (57,405,025 to 57,405,090, forward strand). Ensembl gene ENSG00000266168.
Diseases named in the same sentence as MIR3147 in open-access papers:
MIR3147 is named in the same sentence as 1 disease in open-access papers, as found by Europe PMC text mining. Sharing a sentence is not in itself a finding about the gene and the disease. The quoted sentences say what the papers report.
Hypertension (1 paper, 2023). The presence of chronic increased pressure in the systemic arterial system. "However, the mechanism of other genes, such as TXNL1P1, PIP5K1C, MIR3147, and SLC47A1, underlining hypertension requires further investigation." (PMID 36869404, 2023).